BCL2 (BCL2 apoptosis regulator)
Diseases named in the same sentence as BCL2 in open-access papers (continued):
Sharing a sentence is not in itself a finding about the gene and the disease.
tumor (continued). "Moreover, Bcl-2 was upregulated along with SOX2 and associated with high-grade tumor as well as advanced-stage of HCC." (PMID 34436030, 2021). "Taken together, Lut treatment could significantly enhance Dox-induced tumor cell apoptosis through the Bax/Bcl-2/Caspase-3 pathway in 4T1 and MDA-MB-231 cells." (PMID 34722681, 2021). "Moreover, apigenin reduced tumor growth, promoted tumor cell necrosis, reduced the expression of Ki67, and increased the expression of Bax and Bcl-2 in the xenograft tumors of Huh7 cells." (PMID 33959508, 2021). "Since CTND is a model complex representing a series of similar tumor-insensitive compounds, it is reasonable to believe that this methodology could be expanded to eliminate Bcl-2-induced resistance to other metal complexes." (PMID 34163720, 2021). "The results showed that the nanoparticles could improve the expression of miR-34 in the cells, and then regulate the expression of Bcl-2, Cdk6 and CyclinD1, and play the inhibitory effect of miR-34a on the proliferation and migration of tumor cells." (PMID 34696703, 2021). "In recent years, some studies have pointed out that immunohistochemical analysis showed that not only CD34 and Bcl2 are positive in tumor cells, but also nuclear STAT6 is positive, indicating that the tumor may be a rare variant of SFT." (PMID 33499815, 2021). "High expression of BCL2 was observed in tumor tissues patients with CRC." (PMID 33838016, 2021). "Another mechanism of MDR is the over-expression of the anti-apoptotic protein Bcl-2 in tumor cells." (PMID 34213662, 2021). "It elucidated that loss of ARID1A expression could upregulate the expression of Bcl-2 and contribute to the inhibition of apoptosis of tumor cells." (PMID 34715776, 2021). "Additionally, PTEN, Bax and Beclin1 protein levels were up‐regulated whereas Bcl‐2 and p62 protein levels were down‐regulated in xenograft tumours from nude mice when MEG3 was overexpressed (P < .05)." (PMID 33332708, 2021). "In addition, CK micelles and liposomes can promote tumor cell apoptosis by regulating bax, bcl-2 and caspase-3 of lung cancer cells A549 and PC-9, which can induce mitochondrial apoptosis and damage ROS production." (PMID 34654430, 2021). "Using protein lysates obtained from the xenografted tumor tissues, treatment with flubendazole caused a decrease in the levels of p-STAT3 and induced the expression of apoptosis protein of BAX; meanwhile, the BCL2 level was reduced." (PMID 34513827, 2021). "However, the BAX gene did not significantly increase in the CUR-treated cells, and BAX/BCL2 ratio was significantly increased in B16-F10 tumor cells (P < 0.0001)." (PMID 34825002, 2021). "Additionally, aspirin, a kind of NSAIDs, have been found to induce apoptosis and inhibit tumor invasion by decreasing the expression of B-cell lymphoma 2 (BCL-2) and inhibiting NFκB signaling pathway." (PMID 34123808, 2021). "However, the intrinsic apoptosis pathway is strictly controlled by prosurvival antiapoptotic Bcl-2 proteins and these proteins are often overexpressed in tumor cells and contribute to tumorigenesis and drug resistance." (PMID 34028599, 2021). "Bcl-2 has been recognized as a potential target for the development of novel anti-tumor drugs." (PMID 34638779, 2021). "Moreover, in cells treated only with butyrate, the expression of pro-apoptotic PTEN and anti-tumor TNFα increased (p ≤ 0.05), whereas anti-apoptotic BCL2 was reduced (p ≤ 0.001) compared to PA1B1 treatment." (PMID 34072741, 2021).
tumor (continued). "Besides, the results of H&E and immunohistochemistry staining showed that in hsa_circ_0058493 knockdown group, the positive rate of Ki67, PCNA (tumor proliferation marker) and Bcl-2 (tumor apoptosis marker) in vivo was markedly reduced compared with sh-NC." (PMID 34888309, 2021). "And miR-15/16 act as tumor suppressors by directly targeting BCL2." (PMID 32190086, 2020). "FTO m6A-mediated demethylation of 3'- untranslated region BNIP3 transcript, which is a proapoptotic protein belonging to the Bcl-2 tumor suppressor family, promoting its degradation via YTHDF2 independent pathways and specific upregulation of BNIP3 retards breast cancer proliferation and metastasis." (PMID 33511112, 2020). "Overexpression of miR microARN-203 may serve a role in PTC tumor cells by downregulating Bcl-2 expression." (PMID 33113852, 2020). "As postulated, the addition of BCL-2 inhibitors may sensitize the target tumor cells to perforin/granzyme-B mediated cell kill." (PMID 32131385, 2020). "Overexpression of anti-apoptotic proteins (e.g., Bcl-2 and Bcl-XL) could favor the survival and drug resistance of tumor cells." (PMID 33168044, 2020). "Activation of autophagy promotes tumor metastasis by inducing HIF-1α, and it was verified that HIF-1 modulates the induction of autophagic proteins through regulating the association between Beclin1 and Bcl-2." (PMID 33109128, 2020). "Among these, HIF-1α (hypoxia-inducible factor-1 alpha) induces the expression of BNIP3/BNIP3L (atypical BH3-only proteins the Bcl-2/E1B 19 kDa-interacting protein 3) that, in turn, favors the dissociation of Bcl-2-Beclin1 complexes, activates autophagy and promotes tumor progression." (PMID 33020404, 2020). "Thus, the potential inhibitory effects of LCRF‐0006 on Bcl‐2 and NF‐кB signaling in MM tumor cells warrants investigation in the future." (PMID 32617520, 2020). "In addition, several studies have shown that Bcl-2 overexpression enhances angiogenesis through HIF-1α mediated VEGF secretion in tumor cells." (PMID 32859045, 2020). "One the other hand, AURKA plays a pivotal role in tumor survival by provoking Bcl-2 and MCL-1, and anti-apoptotic factors levels, blocking Bax, Bim, PUMA apoptotic mediators activity, along with disruption of the mammalian Target of Rapamycin (mTOR) autophagy pathway." (PMID 32469983, 2020). "Many studies have been exploring the potential of targeting BCL2 to suppress tumor growth." (PMID 32650615, 2020). "In this study, we found that BPP could significantly inhibit Bcl‐2 expression in both OC cells and xenograft tumours in nude mice, and significantly rose the expression level of Bax." (PMID 32519803, 2020). "Moreover, the uptake and consumption of glucose and lipid was downregulated in DEX-treated tumor or cultured cells and the classic anti-apoptotic marker Bcl2 was significantly inhibited in tumors." (PMID 32156004, 2020). "Previous studies have shown that PRL up-regulates BCL-2 expression in tumor cells." (PMID 33362552, 2020). "In another type of tumor cells, similar findings were obtained for Bax and Bcl-2 attenuation." (PMID 32028721, 2020). "Multiple studies confirmed that the upregulation of the anti-apoptotic proteins of the B-cell lymphoma 2 (BCL2) family mediated by various mechanisms, such as tumor microenvironment, and the activation of intracellular signaling pathways were the major factors leading to resistance to venetoclax." (PMID 33292251, 2020). "Interestingly, Bcl2 and Bax expression patterns in 3D structures replicated human tumor behavior more accurately than 2D cultured cells, in which both biomarkers were overexpressed." (PMID 32286364, 2020). "More importantly, the marked tumor suppression induced by DT2216 was associated with a more than 95% reduction in Bcl-xL levels, substantial decreases in Bcl-2 and Mcl-1 levels, and significant activation of caspase-3 and cleavage of PARP in the tumors collected from the mice." (PMID 32677976, 2020).
tumor (continued). "MiR-34a has been reported as an important mechanism of lead-inhibited tumor invasion and metastasis in OS and its inhibitory role may be partially associated with decreased C-IAP2 and Bcl-2 expression." (PMID 32565738, 2020). "Because our results suggest a dual function of A4 as an inhibitor of both XIAP and Bcl-2, it may be effective against a wide range of tumours over-expressing either one or both these proteins." (PMID 32587235, 2020). "The proteins of Bcl‐2 and Bcl‐xl are crucial inhibitors in the procedure of apoptosis and are commonly overexpressed in many tumors;7, 8 their overexpression is closely related to tumor initiation, aggressive, and chemoresistance." (PMID 32346976, 2020). "Within the bcl-2-driven protumor reprogramming, IL-1β acts as critical upstream regulator of tumor growth and macrophage functions, since its neutralization decreased the expression of COX-2 and IL-17, as well as expression of M2 polarization markers by macrophages." (PMID 32269145, 2020). "The obtained results for IL1β proved tumor supersession which could correlated with results of BCL2 and VEGF proteins." (PMID 32981013, 2020). "Numerous tumor cells avoid apoptosis by upregulating Bcl-2 and Bcl-xL expression." (PMID 33841550, 2020). "The results showed that over‐expressed let‐7a‐1, let‐7d, or let‐7f‐1 resulted in elevated protein expression of c‐Caspase‐3/t‐Caspase‐3 and LC3II/I, while decreased Bcl‐2 and P62 protein expression, with the most significant changes observed in the tumor tissues treated with cluster mimic (P < .01)." (PMID 31868319, 2020). "Also, our data introduce MTX and Nar as promising antiproliferative agents with a distinctive mode of action, inducing apoptosis in HepG2 tumor cells through activation of Bax and down-regulation of Bcl-2 protein expression." (PMID 32458964, 2020). "Interestingly, both CD4+ and CD8+ cells from bcl-2 overexpressing tumor produced lower levels of interferon γ (IFNγ) compared with control ones." (PMID 32269145, 2020). "A Bcl-2 mediated anti-apoptotic effect was seen for TIMPs in tumor cells." (PMID 32560557, 2020). "Furthermore, IHC performed on tumour sections confirmed that IR exposure increased Bcl-2 in these PTEN-null tumours, which was again reversed by x1/2pal-i3-mediated inhibition of CXCR1/2 signalling." (PMID 32743555, 2020). "BCL-2 is a factor that promotes tumor cell proliferation and inhibits tumor cell apoptosis and may be a downstream target gene for the STAT3 signaling pathway." (PMID 33746736, 2020). "Bcl‐2 and Bax can regulate tumor cell apoptosis by regulating Caspase protein activity." (PMID 32750218, 2020). "Earlier studies demonstrated that several BCL-2 inhibitors may stimulate ER stress conditions, including accumulation and aggregation of unfolded and misfolded proteins to manifest their anti-tumor activities." (PMID 33381025, 2020). "This interaction might represent a potential therapeutic approach for Bcl-2-expressing tumours resistant to apoptosis, including GBM10." (PMID 32170186, 2020). "However, as a common mechanism of drug resistance, tumor cell increases the expression of BCL-2 antiapoptotic proteins, conferring resistance to venetoclax in AML cells." (PMID 32679735, 2020). "CircHIPK3 promoted tumor growth, proliferation and metastasis and inhibited apoptosis of RC cells by inhibiting the expressions of C caspase-3, Bax and E-Cad and promoting the expressions of Bcl-2, N-Cad, Vimentin and Ki-67." (PMID 32550826, 2020). "Furthermore, the analysis of data of 3′UTR usage in tumor samples from TCGA confirmed differential BCL2 3′UTR usage in relation to the DSCAM-AS1 expression." (PMID 32503257, 2020).
tumor (continued). "The drug sensitivity of A549-BMP cells to Doxorubicin hydrochloride (DOX) was increased; the growth and migration capability of A549-BMP cells were inhibited along with the decreased protein level of Bcl-2 and DNMT3a; the growth of tumor in nude mice injected with A549-BMP cells were inhibited, too." (PMID 31901898, 2020). "High Bcl-2 levels can inhibit cell apoptosis, accelerate cell growth promote tumor malignancy." (PMID 33014113, 2020). "Here, we investigated tumor-specific BCL2 expression with the automated quantitative analysis (AQUA) scoring system using the multiplex immunofluorescent (IF) imaging to assess the prognostic impact of quantitative BCL2 expression in patients with newly diagnosed DLBCL treated with R-CHOP." (PMID 32606309, 2020). "Therefore, our data support that the sensitivity of tumor cells to BH3 mimetics increases with up-regulating expression of Bcl-2 and Mcl-1." (PMID 33362794, 2020). "Using cutoff values of MYC (40%) and BCL2 (50%) positive tumor cells, twenty-eight (32.2%) were diagnosed as double-expressor lymphoma (DEL), thirty-two (36.8%) as non-DEL and twenty-seven (31%) as unknown." (PMID 33123290, 2020). "Moreover, the systemic injection of miRNA-34a-loaded nanoparticles significantly inhibited tumor growth through the downregulation of Bcl-2 and CDK6 expression and improved the survival of multiple myeloma xenografts in NOD-SCID mice." (PMID 32792960, 2020). "It has also been reported that GS increased the expression of truncated BH3 interacting domain death agonist (Bid), Fas, p-JNK, and p-c-Jun levels in vitro and decreased the expression of cIAP-1, cIAP-2, and Bcl-2, and suppressed tumor growth in an in vivo mouse model." (PMID 36046484, 2020). "Mechanistically, inhibition of the K-ras/GSK3β/NF-kB pathway by the luteolin + gemcitabine combination therapy was found to correlate with reduced tumor cell proliferation and increased apoptosis as confirmed by increased caspase-3 activation and decreased Bcl-2/Bax ratio and cytochrome c release." (PMID 32717779, 2020). "Meanwhile, Bcl-2 expression was higher in shCUEDC1 tumor tissue compared with that in the Ctrl." (PMID 33099540, 2020). "Hence, targeting molecules specific to NEAT1/miR-129/Bcl-2 inside tumor cells can be a novel potential cancer treatment compared to conventional chemotherapy." (PMID 32692721, 2020). "In addition, immunohistochemical staining of BCL-2 gene was performed on formalin fixed paraffin embedded tumor sections." (PMID 32929356, 2020). "The Cers2 gene plays a role in the regulation of cell growth, BCL2 encodes an outer mitochondrial membrane protein that can block apoptosis in cancer cells, PTEN is a tumor suppressor that can be mutated in cancer cells, and MALAT1 is a noncoding RNA that is highly expressed in the nucleus." (PMID 31618108, 2020). "Similarly, a previous study reported that combinatorial therapy of CD19.CAR-T cells with ABT737, a multi-target inhibitor blocking Bcl-2, Bcl-xl and Bcl-w, showed a better anti-tumor activity than either tested individually." (PMID 33362794, 2020). "Notably, patients with tumours with high BCL-2 expression had a significantly worse OS (9.1 versus 12.8 months) (HR 1.63, 95% CI 1.02–2.61, p = 0.038), though high BCL-2 was seen in only a small percentage of samples." (PMID 33298868, 2020). "Bcl-2 promotes survival of tumor cells by binding to pro-apoptotic BAX subfamily members." (PMID 31956363, 2020). "Unfortunately, it appears that unabated apoptosis can have an unanticipated consequence to promote tumor progression, and particularly targeting apoptosis proteins (such as Bcl-2, Bcl-xL, and PI3-kinase) should be considered with adjuvant immunogenic therapeutics." (PMID 33003477, 2020).
tumor (continued). "In the xenograft models, lenvatinib treatment induced significant tumor shrinkage and blocked the proto-oncogene Bcl-2 (B cell lymphoma/leukemia gene-2) and FGFR signaling pathway, along with reduced levels of EMT markers, compared with control and Sorafenib-treated group." (PMID 32075109, 2020). "By contrast, loss of function mutants for ced-9(n2814)/BCL-2, where apoptosis is induced, exhibit no signs of tumor formation upon rpom-1 downregulation." (PMID 31217501, 2020). "Furthermore, pre-treatment of tumor cells with BH3 mimetics resulted in an up-regulation of Bcl-2 and Mcl-1 expression in venetoclax highly sensitive 380 cells and S63845 highly sensitive U698M cells, respectively." (PMID 33362794, 2020). "In pancreatic cancer cell lines, β-sitosterol inhibits tumor cell growth, inducing G0/G1-phase cell cycle arrest, and apoptotic activities, downregulates NF-kB activities, upregulates the expression of Bax, and downregulates the expression of Bcl-2 protein." (PMID 32992537, 2020). "In addition, the pro-apoptosis action in the combination of DW22 and CDDP treatment was further confirmed by the increase of Bax, cleaved PARP, cleaved Caspase3 and decrease of Bcl-2 in A549/CDDP tumor tissues." (PMID 32878625, 2020). "Indeed, while tumor cells are predicted to be more resistant within their microenvironment, they are highly dependent on BCL-2 in peripheral blood." (PMID 32183335, 2020). "The increased miR-451 expression may negatively regulate Bcl-2 mRNA and protein expression, which in turn affects caspase 3 protein expression and accelerates Breast Neoplasms cell apoptosis." (PMID 33193744, 2020). "Of note, an increased expression of IL-17 (IL-17RA), IL-8 (CXCR1) and CCL2 (CCR2) receptors was also observed on M-DM exposed to CM from bcl-2 overexpressing clone, suggesting a larger impact of cancer cell-specific bcl-2 on the interplay between the tumor and the stromal compartment." (PMID 32269145, 2020). "LJGP could inhibit tumor proliferation and induce apoptosis by upregulating pro-apoptotic Bax, and downregulating anti-apoptotic Bcl-2 and IAP family members, as well as activation of caspase-3/9." (PMID 32733246, 2020). "Additionally, Bax activation and Bcl-2 suppression are considered as a promising therapy for tumor treatment." (PMID 32495637, 2020). "Patients with NK/T‐cell lymphoma, another type of EBV‐associated disease, could probably also benefit from treatments with BCL‐2 inhibitors, as high expression of BCL‐2 in the tumor cells has been shown to be associated with a poor prognosis." (PMID 32623836, 2020). "In addition, multiplex IF staining enabled tumor-specific analysis which allowed for BCL2 expression in reactive T-cells to be easily excluded from the analysis." (PMID 32606309, 2020). "It should be noted that the inhibition of the antiapoptotic protein BCL-2 by phenothiazines may help explain its apoptosis-inducing effect on tumor cells." (PMID 32309275, 2020). "In addition, histological and immunohistochemical data showed strong nuclear fragmentation and decreased Bcl-2 and Ki67 cancer marker levels in tumor tissues from mice treated with CDPs." (PMID 32793477, 2020). "Autophagy is a key point on survival and tumor adaptation, whose inhibition decreases anti-apoptotic proteins’ expression (e.g. BCL-2 and survivin) or increases pro-apoptotic proteins, such as BAX, leading to tumor sensitization to photo-stress, e.g. 5-ALA-PDT." (PMID 33552982, 2020). "Early stage high risk adenomas that express BCL-2 might benefit from BCL-2 inhibition with ABT-199, thus preventing tumor progression." (PMID 32335811, 2020). "However, compared to control tissues, the expression of Bcl-2 and Bcl-xl were decreased in mouse tumor tissues." (PMID 32300551, 2020). "Furthermore, western blot results indicated that β-catenin, P-AKT,P-GSK-3β, Cyclin D1, Vimentin, and Bcl-2 protein expression in xenograft tumor were obviously reduced in SC66 treatment group." (PMID 32848734, 2020).